RNU6-960P (RNA, U6 small nuclear 960, pseudogene)
Gene: Small nuclear RNA gene on chromosome 6 (111,091,213 to 111,091,332, reverse strand). Ensembl gene ENSG00000200926.
Homologues: Orthologues: macaque U6 (82% identical), chimpanzee U6 (82% identical), pig U6 (64% identical), guinea pig U6 (62% identical), pig U6 (61% identical), pig U6 (58% identical), rabbit U6 (58% identical), rat LOC120103219 (58% identical), mouse Gm54640 (52% identical), guinea pig U6 (50% identical). Paralogues in human: RNU6-348P (75% identical), RNU6-698P (74% identical), RNU6-1125P (73% identical), RNU6-1145P (73% identical), RNU6-1251P (73% identical), RNU6-38P (73% identical), RNU6-831P (73% identical), RNU6-116P (72% identical), RNU6-1316P (72% identical), RNU6-1318P (72% identical), RNU6-22P (72% identical), RNU6-29P (72% identical), and 1284 more.